AGR2 (anterior gradient 2, protein disulphide isomerase family member)
Description:
Required for MUC2 post-transcriptional synthesis and secretion. May play a role in the production of mucus by intestinal cells (By similarity). Proto-oncogene that may play a role in cell migration, cell differentiation and cell growth. Promotes cell adhesion.
Synonyms: AG-2; hAG-2; AG2; XAG-2; PDIA17; GOB-4; HEL-S-116; HPC8; RIFTD
Tractability: Antibody: UniProt places it where antibodies can reach, with high confidence; its Gene Ontology location is reachable by antibodies, with high confidence; UniProt predicts a signal peptide or a membrane-spanning region.
Gene: Protein-coding gene on chromosome 7 (16,791,387 to 16,833,433, reverse strand). Ensembl gene ENSG00000106541.
Subcellular location: Secreted; Endoplasmic reticulum
Subcellular location (Human Protein Atlas): Endoplasmic reticulum
Gene Ontology:
Molecular function: dystroglycan binding; epidermal growth factor receptor binding; identical protein binding; protein binding; protein homodimerization activity
Biological process: cell chemotaxis; endoplasmic reticulum unfolded protein response; inflammatory response; positive regulation of cell-substrate adhesion; positive regulation of epidermal growth factor receptor signaling pathway; positive regulation of gene expression; positive regulation of IRE1-mediated unfolded protein response; positive regulation of PERK-mediated unfolded protein response; positive regulation of protein localization to plasma membrane; protein folding in endoplasmic reticulum; response to endoplasmic reticulum stress; digestive tract morphogenesis; mucus secretion; positive regulation of developmental growth
Cellular component: endoplasmic reticulum; extracellular region
Genetic constraint (gnomAD): Loss-of-function variants: 21 observed, 22.56 expected, observed/expected ratio (o/e) 0.93, 90% interval 0.66 to 1.34. The upper end of that interval is the gene's LOEUF score, 1.34, which puts it in group 5 of 6, group 1 being the genes least tolerant of losing a copy. Missense variants: 159 observed, 186.55 expected, observed/expected ratio (o/e) 0.85, 90% interval 0.75 to 0.97. Synonymous variants: 68 observed, 65.74 expected, observed/expected ratio (o/e) 1.03, 90% interval 0.85 to 1.27.
Homologues: Orthologues: chimpanzee AGR2 (99% identical), macaque AGR2 (99% identical), dog AGR2 (95% identical), guinea pig AGR2 (95% identical), pig AGR2 (94% identical), rabbit AGR2 (94% identical), mouse Agr2 (91% identical), rat Agr2 (91% identical), zebrafish agr2 (70% identical), tropical clawed frog agr2 (61% identical), Caenorhabditis elegans txdc-12.1 (27% identical), Caenorhabditis elegans txdc-12.2 (25% identical). Paralogues in human: AGR3 (59% identical), TXNDC12 (31% identical).
Diseases named in the same sentence as AGR2 in open-access papers:
AGR2 is named in the same sentence as 138 diseases in open-access papers, as found by Europe PMC text mining. Sharing a sentence is not in itself a finding about the gene and the disease. The quoted sentences say what the papers report.
breast cancer (94 papers, 2003 to 2026). A primary or metastatic malignant neoplasm involving the breast. "In Cluster 5 (IDC), upregulated genes such as CXCL14, S100A11, CCND1, and AGR2 are linked to breast cancer progression, metastasis, and therapeutic resistance." (PMID 41182757, 2025). "Elevated levels of AGR2 expression have earlier also been linked to unfavorable tumor features in breast cancer, prostate cancer, head and neck squamous cell carcinoma, and squamous cell carcinoma of the esophagus." (PMID 39533806, 2024). "Meta analysis of 20 studies including 3285 patients showed that the increased expression of AGR2 was associated with poor overall survival in patients with solid tumors, especially breast cancer." (PMID 37197416, 2023). "LncRNA MEG3 regulates chondrogenic differentiation by inhibiting TRIB2, which is achieved by binding with EZH2 as well as LINC02273; it is associated with hnRNPL, which promotes metastasis of breast cancer by increasing AGR2 transcription." (PMID 38017487, 2023). "AGR2 was detected in disseminated tumor cells by several studies with its expression associated with Luminal subtype and breast cancer metastasis." (PMID 36148946, 2022). "For example, AGR2 is described as an overexpressed gene in ER-positive breast cancer, and a high level of AGR2 is associated with poor prognosis in the same type of breast cancer." (PMID 35159012, 2022). "In breast carcinoma, AGR2 expression in ER a-positive patients is associated with drug resistance to tamoxifen." (PMID 36327302, 2022). "An association between AGR2 and differentiation is also found in breast cancer, where better survival is linked to AGR2." (PMID 34911496, 2021). "More importantly, a variant from of the AGR2 protein was shown to have the ability to be secreted and O-glycosylated by the breast cancer MCF7 cell line." (PMID 31247903, 2019). "Previous studies have shown that increased AGR2 expression is associated with cancer progression and metastasis in breast cancer." (PMID 31856843, 2019). "Accordingly, AGR2 overexpression was found to be associated with chemoresistance in the human breast cancer cell lines MCF7 and MDA-MB23." (PMID 31247903, 2019). "In particular, the analysis for breast cancer patients found the AGR2 overexpression to be significantly associated with poor OS and TTP." (PMID 31247903, 2019). "Two studies have reported an association of increased protein-level AGR2 expression and decreased breast cancer survival using tumor immunohistochemistry." (PMID 29796176, 2018). "Tumor expression of Anterior Gradient 2 (AGR2), an endoplasmic reticulum protein disulfide isomerase, was associated with decreased breast cancer survival." (PMID 29796176, 2018). "AGR2 expression is associated with decreased survival among women with ER+ breast cancer as well as tamoxifen and fulvestrant resistance." (PMID 29796176, 2018). "In breast cancer studies, AGR2 expression is associated with ER-positive tumors and its overexpression is a predictor of poor prognosis." (PMID 30140383, 2018). "In conclusion, we validated the AGR2 survival association in breast cancer and explored various pathways through which AGR2 mediates poor response to treatment and thus decreased disease-specific survival." (PMID 29796176, 2018). "AGR3 is a homologue of AGR2, sharing 71% sequence homology to AGR2 and was initially identified in breast cancer cell lines and both found to be associated with estrogen receptor (ER) positive breast tumours." (PMID 30140383, 2018). "Subgroup analyses indicated that AGR2 overexpression in breast cancer patients was significantly associated with poor OS (HR 3.02, 95% CI 1.03–8.81) and TTP (HR 1.93, 95% CI 1.17–3.20)." (PMID 29138453, 2017). "Of note, subgroup analyses for the solid tumours group with breast cancer excluded showed that AGR2 overexpression was significantly associated with poor OS, but not with TTP." (PMID 29138453, 2017).
breast cancer (continued). "Anterior gradient 2 (AGR2) is a promising anti-tumor target associated with estrogen receptor expression and metastatic progression of breast cancer." (PMID 25956506, 2015). "The clinical and prognostic significance of AGR2 has been demonstrated, suggesting its potential as a tumor diagnostic marker and a modulator in breast cancer anti-estrogen drug resistance." (PMID 25956506, 2015). "Our results demonstrate that expression of AGR2, as measured by immunohistochemistry, is associated with poor outcome in patients with ERα-positive breast cancers." (PMID 16598187, 2006). "In specimens from the 351 breast carcinomas, there was a strong positive association between the presence of immunocytochemical staining for AGR2 and for ERα." (PMID 16598187, 2006). "Interestingly, another research revealed that the low expression of AGR2 is associated with the low overall survival of luminal A and the worst relapse free survival of basal-like breast cancer (BLBC)." (PMID 37197416, 2023). "AGR2 in both breast cancer and prostate cancer is likely may be associated with endocrine status and treatment response." (PMID 36327302, 2022). "In breast cancer patients, AGR2 was associated with poorer survival and increased metastasis." (PMID 32024004, 2020). "Moreover, AGR2 expression is implicated in tamoxifen resistance of breast cancer, probably due to tamoxifen-induced AGR2 expression." (PMID 25367337, 2014). "In addition, induction of AGR2 expression by tamoxifen through AKT or Src has been implicated in tamoxifen resistance of breast cancer cells." (PMID 25367337, 2014). "Thus, we identified a novel H6PD interactor, i.e. AGR2, started to explore breast cancer hallmark pathways to which this interaction might contribute to, and provided evidence that AGR2 enhances H6PD activity." (PMID 40281598, 2025). "Serum samples from 154 dogs with mammary tumors (31 benign, 123 malignant) and 39 healthy controls were analyzed using a custom multiplex immunoassay detecting autoantibodies against AGR2, HAPLN1, IGFBP5, and TYMS, normalized to anti-BSA levels." (PMID 41562247, 2026). "First, the TCGA database was used to analyze H6PD and AGR2 mRNA expression correlation in breast cancer subtypes, and contribution of the two genes for survival of breast cancer patients." (PMID 40281598, 2025). "Three different breast cancer cell lines were analyzed for their AGR2 and H6PD protein expression levels by immunoblotting to identify a suitable cell line for Co-IP experiments." (PMID 40281598, 2025). "These included, among others, pathways related to energy adaptation in breast cancer, such as fatty acid metabolism and glycolysis that were found to be enriched in breast cancer tissues, with elevated AGR2 or H6PD expression." (PMID 40281598, 2025). "18A4 also inhibits the growth of MCF-7 breast cancer cells in vitro by inhibiting extracellular AGR2." (PMID 40867591, 2025). "Due to its known association with breast cancer, we examined the PDI Anterior gradient protein 2 (AGR2) as H6PD interacting partner." (PMID 40281598, 2025). "These pathways have been shown to contribute to breast cancer progression, highlighting the importance of the potential AGR2 and H6PD interaction." (PMID 40281598, 2025). "Due to its high score in the BioID screening and its reported role in breast cancer, anterior gradient protein 2 (AGR2) was selected for a more detailed analysis." (PMID 40281598, 2025). "In terms of microRNA, hsa-mir-135b has been identified as a target for treating AGR2-expressing breast cancer with doxorubicin resistance." (PMID 38254021, 2024). "Pancreatic cancer, non-small cell lung cancer, colon cancer, and breast cancer exhibit drug resistance via AGR2 involvement." (PMID 39062458, 2024). "Studies have shown that AGR2 is involved in cellular survival and the development of tamoxifen resistance in breast cancer." (PMID 39533806, 2024).
breast cancer (continued). "In breast cancer, AGR2 has been identified as a marker for tumor invasion, metastasis, and prognosis." (PMID 39062458, 2024). "Antibodies directed against AGR2 were able to reduce tumor growth in endocrine therapy‐resistant breast cancer." (PMID 39533806, 2024). "The role of AGR2 in elevating mucin levels to influence cancer invasion has been observed in various cancers, including pancreatic, colon, and breast cancers." (PMID 39062458, 2024). "For instance, AGR3 had already been characterized as a novel potential biomarker both for breast cancer prognosis and early breast cancer detection, while AGR2 expression has been correlated with poor outcomes of patients with ER-positive breast cancer." (PMID 39580456, 2024). "Previous studies showed that the expression of AGR2 in breast cancer cells required the transcription factor FOXA1." (PMID 37568077, 2023). "Its endoplasmic reticulum retention sequence, protein disulfide isomerase active site and multiple protein binding sequences endow AGR2 with diverse functions inside and outside breast cancer cells." (PMID 37197416, 2023). "AGR2 was first identified in the estrogen receptor-expressing MCF-7 breast cancer cell line and was found to be regulated by estrogen both in vitro and in vivo." (PMID 36899352, 2023). "siRNA-mediated AGR2 knockdown induces cell death, inhibits cell growth and arrests cell cycle progression in breast cancer cells." (PMID 36899352, 2023). "Knockdown of AGR2 can reduce IGF-1-induced cell proliferation, migration and cell cycle progression, which indicates that AGR2 is a key regulator involved in the development of IGF-1-induced breast cancer." (PMID 37197416, 2023). "The results showed that the average value of AGR2 in healthy control group was 2.93 ± 0.42 ng/ml (n = 56), that in breast cancer group was 5.62 ± 0.87 ng/ml (n = 118), and that in breast cancer metastasis group was 13.7 ± 3.2 ng/ml (n = 23)." (PMID 37197416, 2023). "The first antibody developed against AGR2 is a mouse monoclonal antibody, called 18A4, which has been proved to inhibit the growth of breast cancer cells in vitro." (PMID 37197416, 2023). "The prognostic role of either forkhead box A1 (FOXA1) or anterior gradient 2 (AGR2) in breast cancer has been found separately." (PMID 37568077, 2023). "Dr Roman Hrstka (Masaryk University, Brno, Czech Republic) focused on investigating the AGR2 interactome in breast cancer models." (PMID 37409695, 2023). "The stability of the dimer can be changed by studying a drug precursor to mediate the disorder region at the N-terminal of the protein, thus affecting the function of AGR2 in breast cancer." (PMID 37197416, 2023). "A study aimed to identify biomarkers of HER2 dependent breast cancer by proteomic methods found that AGR2 was overexpressed in more than 40% of HER2 positive breast cancer." (PMID 37197416, 2023). "This article focuses on the research progress of AGR2 and the occurrence, development and clinicopathological relationship of breast cancer." (PMID 37197416, 2023). "In the present study, therefore, the statistical interaction between FOXA1 and AGR2 on breast cancer prognosis was explored." (PMID 37568077, 2023). "Combining AGR2 with other tumor markers can improve the sensitivity of breast cancer diagnosis, which is one of the hot spots that clinicians need to pay attention to in the future." (PMID 37197416, 2023). "When LINC02273 is combined with AGR2, it can be used as an independent prognostic factor to predict overall survival in patients with breast cancer." (PMID 37197416, 2023). "The development and application of AGR2 targeted monoclonal antibodies, selective peptides and microRNAs can inhibit the growth and migration of breast cancer cells and enhance drug sensitivity." (PMID 37197416, 2023).
breast cancer (continued). "With the deepening of research, we found that the high expression of AGR2 marks the possible metastasis of breast cancer, which is one of the indicators of poor prognosis of breast cancer patients." (PMID 37197416, 2023). "For example, the AGR2 mouse monoclonal antibody has already been developed and was shown to suppress the growth of breast cancer cells." (PMID 35965326, 2022). "Derepression of AGR2 was not only found in breast cancer cells, but also in other common adenocarcinomas, including those derived from the esophagus, stomach, lungs, pancreas, ovaries, and prostate." (PMID 36327302, 2022). "AGR2 was initially found in human breast cancer specimens, and it is a member of the disulfide isomerase family of endoplasmic reticulum (ER) proteins that catalyze protein folding and thiol-disulfide interchange reactions." (PMID 36327302, 2022). "Both cell lines increased nuclear Caspase-3 activation following a slight reduction in AGR2, a feature seen previously in primary breast cancer cells." (PMID 36482387, 2022). "It was discovered as a new protein whose sequence is highly homologous to AGR2 in a proteomics analysis from enriched plasma membrane proteins of breast cancer cell lines and was initially named BCMP11." (PMID 35965326, 2022). "METTL3 regulated MALAT1/E2F1/AGR2 pathway and subsequently controlled Adriamycin resistance in breast cancer." (PMID 36212476, 2022). "AGR2 is overexpressed in several human cancers, including lung cancer, colon cancer, breast cancer, and ovarian cancer." (PMID 35055132, 2022). "Our data indicate that decreased expression of SOX2 and AGR2 with low serum level of serum AGR2 clearly related to breast cancer patients who respond and had benefit from tamoxifen-based therapy." (PMID 34567804, 2021). "AGR2, strongly associated with ER-positive breast cancer, is up-regulated in luminal A and B subtypes as well as HER2-positive breast cancer." (PMID 33717413, 2021). "AGR2 represses apoptosis in cancers, including pancreatic cancer, cervical cancer and breast cancer." (PMID 34793477, 2021). "The expression of AGR2 is elevated in multiple cancers, including lung cancer, breast cancer, prostate cancer, and ovarian cancer." (PMID 34925322, 2021). "Recent work indicated that LINC02273 epigenetically promoted AGR2 transcription and drove breast cancer metastasis." (PMID 34618681, 2021). "In breast cancer cells, the expression levels of AGR2 protein positively correlated with the protein levels of the β-DG subunit but not that of the α-DG subunit of dystroglycan." (PMID 33717413, 2021). "First, we selected three representative breast cancer cell lines with differential AGR2 expression (MDA-MB-231, MCF7, and MDA-MB-453 cells) and compared the protein levels of β-DG." (PMID 33717413, 2021). "AGR2 expression was recognized to correlate with dissemination and bad prognosis in breast cancer and reported as a biomarker in prostatic cancer." (PMID 34567804, 2021). "LINC002273 was reported to be correlated with tumor proliferation, migration, and invasion by epigenetically increasing the AGR2 transcription in breast cancer." (PMID 35004851, 2021). "Elevation of CCND1 and AGR2 mRNA levels were also observed in the ERα (-) breast cancer cells treated with LDN." (PMID 32042339, 2020). "For example, siRNA-mediated AGR2 knockdown inhibited cells growth, arrested cell-cycle and induced cells death in breast cancer cells." (PMID 33005802, 2020). "Alternatively, AGR2 was regarded as a binding stabilizer of HIF1α, thereby contributing to the hypoxia-induced doxorubicin resistance in breast cancer." (PMID 32322663, 2020). "A recent study shows that UBR5 was responsible for polyubiquitination of anterior gradient 2 (AGR2), a protein that was first identified as being downregulated in breast cancer cell lines via sequencing data." (PMID 32867711, 2020). "In human cells, the agr2 gene was first discovered in the estrogen receptor-positive MCF-7 breast cancer cell line." (PMID 33005802, 2020).